G6PD (glucose-6-phosphate dehydrogenase)
Diseases named in the same sentence as G6PD in open-access papers (continued):
Sharing a sentence is not in itself a finding about the gene and the disease.
tumor (continued). "Specifically, the loss of FOXO1 increased apoptosis in HCT116 and MDA-MB-231 cells treated with H2O2 (100 μM), which was partially reversed by overexpressing G6PD or adding NAC, while overexpression of FOXO1 alone significantly decreased tumor cell apoptosis." (PMID 41124013, 2025). "Mechanistically, HPV16 E6 inhibited G6PD K45 site lactylation to increase G6PD enzyme activity, leading to elevated PPP activity, which is commonly overactivated in tumor cells." (PMID 39925738, 2025). "Overall, these results confirmed that G6PD was a pivotal downstream target of BANCR, playing a significant role in the tumor-suppressive function mediated by BANCR in ccRCC." (PMID 39894218, 2025). "Inhibition of G6PD can decrease NADPH production, leading to impaired nucleotide synthesis and cell cycle arrest, which subsequently inhibits tumor cell proliferation and the immunosuppressive functions of MDSCs." (PMID 39990210, 2025). "The interaction between G6PD, DNMT1, and BCAT1 in tumors presents an opportunity to develop new treatment methods that target tumor metabolism." (PMID 41462671, 2025). "Aspirin was also reported to affect the activity of glucose-6-phosphate dehydrogenase (G6PD), which plays a crucial role in sustaining tumor growth." (PMID 41439989, 2025). "The increased expression of G6PD can activate PPP, thereby reducing platinum-induced oxidative stress and gradually inducing tumor resistance." (PMID 40227333, 2025). "The expression levels of G6PD, HMGA1, MKI67, RACGAP1, and RFC4, were significantly higher in tumor samples with (p < 0.05)." (PMID 40421085, 2025). "PIk1, acting as a cell mitotic regulator, directly binds to G6PD, facilitating the formation of its active dimer and activation of the PPP, thereby driving cell cycle progression and tumor cell growth." (PMID 39894218, 2025). "G6PD inhibits ferroptosis in HCC cells, while its knockdown reduces tumor volume and weight in vivo." (PMID 40136455, 2025). "For instance, a study demonstrated that inhibiting glucose-6-phosphate dehydrogenase (G6PD) in the PPP, combined with Trx system suppression, significantly elevates oxidative stress in tumor cells." (PMID 39859211, 2025). "Next, to study the tumorigenic capacity of G6PD in vivo, we subcutaneously transplanted HepT1 cell-shNC, HepT1 cell-NAT10, and HepT1 cell-NAT10-shG6PD into nude mice and monitored the tumor sizes timely." (PMID 40303290, 2025). "Subsequently, deacetylation decreases G6PD ubiquitination and enhances SUMO1 modification, increasing G6PD stability, promoting tumour cell proliferation and inhibiting apoptosis." (PMID 39778006, 2025). "Compared to normal samples, G6PD and KPNA2 exhibited significant expression peaks in the early cellular phases in tumor samples, and more homogeneous expression distribution was displayed in normal samples." (PMID 40307857, 2025). "G6PD catalyzes the PPP’s first step, generating NADPH that is essential for redox balance and macromolecular biosynthesis in rapidly proliferating tumor cells." (PMID 39519266, 2024). "G6PD was the rate-limiting enzyme in the PPP and maintained redox balance in tumor cells by generating NADPH." (PMID 39516455, 2024). "Through a combination of RNA sequencing and MeRIP-sequencing, we identified numerous altered genes and confirmed that IGF2BP2 enhances G6PD mRNA stability after METTL14-mediated m6A modification, thereby promoting tumor growth and metastasis." (PMID 39138186, 2024). "The qRT−PCR analysis revealed that upregulated expression of CTSC, CDCA8, and G6PD, whereas downregulated expression of CXCL9 in HCC compared with adjacent tumor tissue and normal liver cell lines." (PMID 38742112, 2024).
tumor (continued). "Mechanistically, we found that METTL14 up-regulates G6PD expression through an m6A-IGF2BP2-dependent pathway, contributing to tumor growth and metastasis in glycolytic microenvironments." (PMID 39138186, 2024). "We subsequently investigated the role of pharmacological inhibition of G6PD, in combination with autophagy inhibitors, on inhibiting DCBDL1-mediated tumor proliferation." (PMID 38291438, 2024). "Results revealed elevated Fra-1 expression in tumor tissues from the Fra-1 overexpression group and Fra-1 overexpression + CDDP group compared to the NC group, accompanied by increased G6PD expression." (PMID 39624082, 2024). "The PPP, vital for the synthesis of ribonucleotides and NADPH, induces an upregulation of glucose-6-phosphate dehydrogenase (G6PD) in cancerous tissues, a response to the oxidative stress endemic in tumor microenvironments." (PMID 39456607, 2024). "CCL5 and CCL18 upregulate various glycolysis-promoting factors, including hexokinase 2 (HK2), phosphoglycerate kinase 1 (PGK1), glucose-6-phosphate dehydrogenase (G6PD), and pyruvate kinase, further facilitating tumor progression." (PMID 38714539, 2024). "Our present study reveals that PBX3 is essential for glucose metabolism in tumor cells, specifically, we identify PBX3 as a novel transcriptional regulator of G6PD that binds directly to the G6PD promoter and enhances its activity." (PMID 37781025, 2023). "Glucose-6-phosphate dehydrogenase (G6PD) is the rate-limiting enzyme of the pentose phosphate pathway and the primary actor in PPP-mediated tumor progression." (PMID 37981593, 2023). "G6PD is the largest contributor to NADPH production, while NADPH promotes tumor resistance to ROS and ferroptosis." (PMID 37315289, 2023). "Given that p52-ZER6 positively regulates G6PD levels, we investigated the effect of p52-ZER6 on NADPH, a metabolic intermediate of the PPP that protects tumor cells from oxidative stress." (PMID 36977688, 2023). "Glucose entering the tumor cells can be metabolized by the PPP, and G6PD is the key rate-limiting enzyme in this process." (PMID 38139250, 2023). "The qRT-PCR results demonstrated that four cellular senescence-related genes (CENPA, CXCL8, EZH2, and G6PD) and two chemokine-related genes (CCL26 and CXCL5) were overexpressed in tumor tissues from HCC patients compared with paraneoplastic tissues." (PMID 36670201, 2023). "Activation of G6PD/PPP leads to increased anti-oxidant activity to counteract ROS induced by anti-tumor therapies, thus promoting tumor cell drug resistance." (PMID 38139067, 2023). "The IHC expression of G6PD in primary and metastatic RCC tumours and adjacent normal tissue was evaluated." (PMID 37174052, 2023). "Using serial sections of the xenografted tumor, we performed in situ hybridization and immunohistochemistry staining, and confirmed a decrease in p52-ZER6 and G6PD expression in xenografted tumors formed by p52-ZER6-silenced HCT116p53null cells." (PMID 36977688, 2023). "We identified two new (Y249 and Y322) phosphorylation sites influenced by the tumor metabolic microenvironment lactic acid sensing by GSTP1, which frees up G6PD from a tripartite complex to facilitate the PPP oxidative branch." (PMID 37491277, 2023). "G6PD is also involved in the regulation of EMT and, eventually, the migration and invasion potential of tumor cells." (PMID 38139067, 2023). "LGALS3 and G6PD were highly expressed in the CHI, S2-S4, and tumor groups, and PINK1 was highly expressed in the normal, S0-S1 and paracancerous tissues." (PMID 37180150, 2023).
tumor (continued). "HK2 has high expression levels in many types of human tumor, together with increased expressions of phosphofructokinase (PFK), other glycolytic enzymes, and glucose-6-phosphate dehydrogenase (G6PD)." (PMID 35216280, 2022). "The levels of glycometabolism-related hub genes (G6PD, CENPA, STC2, and PFKFB4) in tumor samples were higher than those in normal samples (p < 0.001)." (PMID 35938165, 2022). "Previous studies revealed that G6PD is a key energy metabolism gene for HCC and contributes to tumor proliferation, migration, and invasion." (PMID 36263042, 2022). "Three identified candidate genes, FADS2, KIF20A, and G6PD, were highly expressed in LUAD tissues and their high expression correlated with poor patient prognosis, and tumor stage." (PMID 36225575, 2022). "In summary, five of the genes (CARS1, CHAC1, FANCD2, G6PD, and HMOX1) in the prognostic model have been reported to contribute to ferroptosis and to be upregulated in BC tumor tissue, in contrast to AIFM2." (PMID 36313179, 2022). "Increased G6PD expression, at both the mRNA and protein levels, in different tumour tissues increases PPP activity and promotes tumour cell growth and survival." (PMID 35712981, 2022). "We report for the first time that Trx-1 regulates the activity of G6PD by interacting with it to regulate NADPH homeostasis and maintain tumor cell survival." (PMID 36147458, 2022). "Polydatin, an active ingredient extracted from the traditional Chinese medicine Polygonum multiflorum, was identified to inhibit the activity of G6PD enzymes and NADPH in a dose-dependent manner thus suppress the growth and metastasis of tumor cells." (PMID 36091812, 2022). "The results revealed that the mean methylation levels of G6PD, HELLS, RRM2, and STMN1 were significantly lower in HCC tissues than in peri-tumor tissues." (PMID 36304446, 2022). "Xn can regulate other pathways by covalently modifying cysteine residues in proteins, such as partially inhibiting glucose-6-phosphate dehydrogenase, limiting the production of NADPH, and inhibiting tumor growth." (PMID 36408214, 2022). "Three genes (SQSTM1, G6PD, and CDK1) were classified into risky group with HR >1 related to poorer prognosis and presented higher expression levels in tumor tissues than in normal tissues." (PMID 35711939, 2022). "For instance, the expression and activity of glucose-6-phosphate dehydrogenase (G6PD), a rate-limited enzyme in the oxidative PPP pathway, is tightly regulated by several oncoproteins and tumor suppressors." (PMID 35453346, 2022). "Three genes (SQSTM1, G6PD, and CDK1) were upregulated in the tumor tissues compared to the HCC normal tissues in the TCGA-LIHC dataset." (PMID 35711939, 2022). "More interestingly, Cyclin E1 could be mediated by G6PD overexpression and high Cyclin E1 expression predicted poor outcomes, which indicated that as a cell cycle-related molecular, Cyclin E1 might be a more crucial downstream target of G6PD in promoting ccRCC tumor proliferation." (PMID 34975298, 2022). "G6PD is the core enzyme of the pentose phosphate pathway (PPP) in glucose metabolism and is involved in tumor cell growth, invasion, and metastasis." (PMID 35938165, 2022). "Glucose-6-Phosphate Dehydrogenase (G6PD) is the rate limiting enzyme of the PPP, and its inhibition can induce autophagy and senescence in tumor cells, as well as inhibit their proliferation and metastasis." (PMID 36479131, 2022). "As proof, the glucose-6-phosphate dehydrogenase–NADPH redox system indirectly activated T cells and advances alleviate T cell hypofunction in the tumor microenvironment." (PMID 34778061, 2021). "The T‐CHO and TG contents were measured in tumour tissue, and the results showed that the levels of T‐CHO and TG in TSP50 and wild‐type G6PD‐expressing group are significantly higher than those in other two groups." (PMID 33630390, 2021).
tumor (continued). "Glucose-6-phosphate dehydrogenase (G6PD) and hexokinase 2 (HK2) are key enzymes in glucose metabolism and play important roles in regulating tumor growth, metastasis, apoptosis, vasculature, and autophagy." (PMID 33718248, 2021). "At the 7th day of the experiment, the tumor volume was determined every three days, and the AGS cells with silence of G6PD visibly generated smaller tumor compared with that tumor in the sh-NC group (P < 0.01)." (PMID 33514309, 2021). "It demonstrated that the expression of G6PD, EGFR, CHMP6 and PROM2 were elevated in the tumor tissues." (PMID 34885178, 2021). "Glucose‐6‐phosphate dehydrogenase (G6PD), the rate‐limiting enzyme of the PPP, is previously reported to be elevated in HCC and contributes to tumour growth by producing ribose‐5‐phosphate and NADPH through the PPP." (PMID 33630390, 2021). "Hypoxia induces the glycosylation and activation of glucose-6-phosphate dehydrogenase (G6PD), the rate-limiting enzyme of the pentose phosphate pathway (PPP), to promote the PPP and tumor growth." (PMID 33681231, 2021). "The tumor tissues of patients with different pathological stages were detected, mainly for the expressions of HPV16 E6 and G6PD protein /mRNA, and the correlation between them was analyzed." (PMID 34692493, 2021). "As we have mentioned, Glucose-6-phosphate dehydrogenase (G6PD) is a rate-limiting enzyme of the pentose phosphate pathway and a tumor promoter in numerous tumor types." (PMID 33514309, 2021). "Taken together, these results demonstrate that G6PD and its activity regulated by acetylation and deacetylation are critical for TSP50‐mediated tumour growth in vitro and in vivo." (PMID 33630390, 2021). "We used immunohistochemistry (IHC) to analyze the expression patterns of G6PD and TKT in pancreatic tissues from genetically engineered spontaneous tumor-producing KPC mice and human PDAC tissues." (PMID 33664869, 2021). "In support of these results and importantly, analysis of the TCGA and SU2C PC tumor datasets demonstrated that MUC1 significantly correlates with activation of the NFE2L2.V2 signature and SLC7A11 and G6PD gene expression." (PMID 34163028, 2021). "Between the two groups, tumour tissue had significantly upregulated G6PD (p < 0.0001), unaltered 6PGD, and PHGDH and PSAT1 were significantly downregulated (p < 0.0001), versus the non-tumour tissue." (PMID 33028928, 2020). "Subsequently, the expression of G6PD, p-STAT3, and p65 in tumor xenografts was compared by Western blot analysis." (PMID 33041664, 2020). "Pentose phosphate pathway (PPP) that is catalyzed by glucose-6-phosphate dehydrogenase (G6PD) and 6-phosphogluconate dehydrogenase (6PGD) provides tumor cells the ribose-5-phosphate and NADPH." (PMID 32276589, 2020). "Four genes, G6PD, APLP1, GCNT3, and PLPP2, were also over-expressed in advanced stage (III and IV) and high grade (3 and 4) ccRCC and tumor with necrosis (PADJ<0.05)." (PMID 30603059, 2018). "The median ITGA4 gene to control G6PD gene mRNA expression ratio in GIST was 6.7 (range = 0.18–15.94, P = 0.002) and in other tumours 2.1 (range = 0.10–6.23)." (PMID 29377440, 2018). "It participates in the regulation of the antioxidant defense, chemoresistance, tumorigenesis and tumor progression, in part by promoting anabolic reactions such as those catalyzed by TKT and G6PD." (PMID 29290982, 2017). "We observed that while overexpressing G6PD promoted tumor growth in vivo, BI2536 treatment dramatically suppressed it even when G6PD was overexpressed." (PMID 29138396, 2017). "In vivo studies reinforced the relevance of G6PD in HCC progression, as G6PD suppression inhibited tumor growth in Huh7 orthotopic tumor and mouse xenograft models." (PMID 28553614, 2017).
tumor (continued). "Costunolide-mediated decrease in tumor volume was accompanied by decreased expression of TERT, Nrf2, G6PD, TKT, and GS(P) levels." (PMID 27148686, 2016). "Given the beneficial effects of HDAC inhibition on bulk tumor cells, combination therapies with HDAC inhibition and G6PD inhibitors in patients with high-G6PD-expressing tumors is an attractive combination for future study." (PMID 27078845, 2016). "Beginning in the late 1970-ies data regarding glucose-6-phosphate dehydrogenase (G6PD)—especially those relating to cell proliferation, oxidative defence and tumor growth—were recorded and analyzed." (PMID 27872579, 2016). "G6PD expression transforms NIH3T3 fibroblasts and induces tumor development in nude mice, indicating that G6PD acts as an oncogene." (PMID 27861141, 2016). "miRNAs modulate the expression of numerous metabolic factors and enzymes, such as SREBF2, AKT2, G6PD, CPS1, FADS1, and ETNK1, which alter tumor cell responses to chemotherapeutic treatments." (PMID 27861141, 2016). "The correlation of G6PD expression and tumor growth corresponded with STAT3/STAT5 expression, although further experiments will be required to confirm the direct regulatory role of G6PD on this pathway." (PMID 23693134, 2013). "Glucose-6-phosphate dehydrogenase (G6PD), elevated in tumor cells, catalyzes the first reaction in the pentose-phosphate pathway." (PMID 23693134, 2013). "Notably, G6PD was predominantly expressed in early and mid-stages, while KPNA2, PFKP, and TPX2 were upregulated in advanced tumor states." (PMID 40307857, 2025). "After describing the individual roles of the ferroptosis-related genes (G6PD, KIF20A, EZH2, NT5DC2, SLC7A11), it is essential to investigate how these genes might interact with each other to influence the tumor microenvironment (TME) in a synergistic manner." (PMID 40465746, 2025). "Similarly, G6PD and HSP90AA1 exhibited notably increased protein expression in tumor tissues compared to normal controls." (PMID 40299459, 2025). "To verify whether TREM2+ macrophages regulate the expression of PKM, G6PD, and ALDOA in tumor cells, we detected their levels in Hepa 1–6 cells treated with CM from WT or Trem2−/− BMDMs." (PMID 39838454, 2025). "For example, silencing G6PD with lentivirus or non-viral gene delivery vector enhances oxaliplatin anti-tumor effects in CRC xenografts and PDX models." (PMID 39859324, 2025). "Notably, analysis of the TCGA database and HB tumor tissue samples revealed a positive relevance between NAT10 and G6PD expression." (PMID 40303290, 2025). "We identified six signature LRGs (ALB, G6PD, HMGA1, MKI67, RACGAP1, and RFC4) possess prognostic potential, correlation with immune infiltration, and lactylation-related pathways, providing novel insights into tumor microenvironment (TME) of HCC." (PMID 40421085, 2025). "The analysis results showed that the expression levels of G6PD, KIF20A, NDRG1, RECQL4, and MCM4 were significantly higher in HCC tumor tissues than in normal tissues, while ADH1C was significantly downregulated in HCC tumor tissues." (PMID 41169384, 2025). "Finally, seven prognostic genes-ADH5, FAM162A, HS2ST1, INSR, G6PD, GLCE, and SDC3-were found to have the strongest correlation with tumor metastasis." (PMID 38586328, 2024). "G6PD ablation in KL lung tumors did not completely inhibit the tumor growth, suggesting the presence of metabolic reprogramming or compensation during tumor progression." (PMID 38997257, 2024). "Increasing evidence has revealed that alteration in nutrition metabolism can lead to aberrant O-GlcNAcylation, which directly modifies metabolic enzymes such as PGK1, PFK1, G6PD, PKM2 and MDH1 to reprogram metabolic pathways, thereby contributing to tumor growth." (PMID 38778217, 2024).